USP7 (ubiquitin specific peptidase 7)
Diseases named in the same sentence as USP7 in open-access papers (continued):
Sharing a sentence is not in itself a finding about the gene and the disease.
osteosarcoma (6 papers, 2015 to 2024). A usually aggressive malignant bone-forming mesenchymal neoplasm, predominantly affecting adolescents and young adults. "We also revealed that loss of USP7 inhibited the E2 content and enzymes Cyp19a1 and Cyp11a1, which suggested that mTORC1 stabilized USP7 may positive regulate E2 synthesis in osteosarcoma." (PMID 38467635, 2024). "This, together with its other activities, makes USP7 a key target for osteosarcoma treatment, and so it is a focal point of research." (PMID 38534381, 2024). "For example, USP7 is known to be upregulated in osteosarcoma, but its ability to increase MDM2 levels in that context has not been investigated." (PMID 38534381, 2024). "Compared to paired adjacent normal tissues, USP7 is significantly upregulated in osteosarcoma (OS) tumor tissues, and high expression levels of USP7 are positively correlated with TNM staging and metastasis in OS patients." (PMID 39062505, 2024). "In addition, mTOR complex 1 (mTORC1) is involved in the occurrence and development of osteosarcoma by regulating the stability of USP7 mRNA." (PMID 39062505, 2024). "Moreover, HIF-1α can be regulated by USP7, which is upregulated in osteosarcoma and has been found related to the activation of EMT." (PMID 38534381, 2024). "In osteosarcoma (OS), overexpression of USP7 significantly improves the ability of cell migration and invasion, while USP7 depletion has the opposite effects, indicating the key role of USP7 in regulating the migratory and invasive ability of osteosarcoma cells." (PMID 34869041, 2021). "Micafungin has been found in drug studies to induce apoptosis in osteosarcoma cells and prevent epithelial–mesenchymal transition (EMT) in a USP7/AKT/GSK-3β pathway-dependent manner, exerting anti-tumor effects." (PMID 39062505, 2024).
hypogonadism (5 papers, 2021 to 2025). A disorder characterized by decreased function of the gonads. "Because Usp7 was reportedly found mutated in XY patients exhibiting hypogonadism, we also investigated the phenotype of mutant testes." (PMID 38517962, 2024). "USP7 encodes an essential DUB for which disruption of one allele, whether via heterozygous deletions or nonsense/missense mutations, results in Hao-Foutain syndrome, a developmental disorder with seizures, behavioral abnormalities, hypogonadism, and hypotonia." (PMID 33335288, 2021).
lymphoma (5 papers, 2018 to 2025). A malignant (clonal) proliferation of B- lymphocytes or T- lymphocytes which involves the lymph nodes, bone marrow and/or extranodal sites. "Additionally, Kaplan-Meier survival analysis across multiple databases showed that high USP7 expression in lymphoma patients is associated with poor prognosis." (PMID 40713963, 2025). "USP7 is overexpressed in lymphomas in dogs, and P5091 is an inhibitor that has cytotoxic effects in canine lymphoma and cancer cells." (PMID 39664521, 2024). "USP5/IsoT, USP7/HAUSP, USP9, and USP15i are higher expressed in EBV-transformed lymphoblastoid cell line (LCL) than in the Burkitt’s lymphoma cell line Raji." (PMID 35158879, 2022). "This suggests that USP7 may play a critical role in regulating DDR1 expression and could potentially serve as a prognostic biomarker in lymphomas." (PMID 40713963, 2025).
osteoarthritis (5 papers, 2023 to 2026). A noninflammatory degenerative joint disease occurring chiefly in older persons, characterized by degeneration of the articular cartilage, hypertrophy of bone at the margins and changes in the synovial membrane. "Inhibition of USP7 by its inhibitors promoted cartilage destruction in osteoarthritis mice via activation of the BiP-eIF2α-ATF4-CHOP pathway in ERS and promotion of NF-κB/p65 pathway." (PMID 37359559, 2023). "P22077, one USP7 inhibitor, repressed osteoarthritis process in mice with monosodium iodoacetate (MIA) injection." (PMID 37359559, 2023). "USP7 expression was decreased in the knee joint cartilage of mice with osteoarthritis." (PMID 37359559, 2023). "Hence, USP7 regulated NOX4/ROS/NLPR3 pathway to contribute to osteoarthritis progression." (PMID 37359559, 2023). "Hence, upregulation of DDAH1 to inhibit ADMA levels and regulate USP7-mediated SOX9 deubiquitination could be a useful strategy for the treatment of osteoarthritis." (PMID 37359559, 2023). "This interaction disrupts USP7-mediated deubiquitination and leads to SOX9 degradation in osteoarthritis." (PMID 40240356, 2025). "Previous study confirmed that USP7 aggravated hypoxia‐induced cardiomyocyte apoptosis and inflammation in myocardial infarction, and accelerated pyroptosis, oxidative stress, and inflammation of H2O2‐induced chondrocytes in osteoarthritis." (PMID 40329406, 2025). "In addition, USP7 and NOX4 were highly expressed in osteoarthritis patients." (PMID 37359559, 2023).
Autoimmunity (4 papers, 2019 to 2025). The occurrence of an immune reaction against the organism's own cells or tissues. "Besides, the conditional deletion of USP7 in Tregs leads to a dramatic loss of immune regulation and to lethal autoimmunity, indicating the need to counteract the process of Foxp3 ubiquitination in order to maintain a functional and stable pool of Tregs in periphery." (PMID 31824482, 2019). "We have also shed light on the mechanisms by which USP7 controls IRF4 and IRF8 expression in cDCs in the context of autoimmunity." (PMID 40247205, 2025). "Previous studies have indicated that the interaction between USP7 and EZH2 can also play a role in the regulation of immune response and inflammation, processes that are relevant to conditions such as autoimmunity and cancer." (PMID 39310812, 2024).
diabetes (4 papers, 2022 to 2025). "USP7 knockdown reduces inflammation and pancreatic acinar cell injury during acute pancreatitis progression by inhibiting autophagy activation; additionally, USP7 is an essential regulator for driving pancreatic endocrine lineage development, which may cause post-pancreatitis diabetes mellitus." (PMID 41145464, 2025). "Our findings underscore the role of the USP7/Ezh2 axis in maintaining tolerogenic DC functions that are required to tailor adaptive immune response and diabetes protection in NOD mice." (PMID 40247205, 2025). "Importantly, the capacity of Stat5b-CA.DCs to protect NOD mice from diabetes were lost when treated with USP7 inhibitor." (PMID 40247205, 2025). "Moreover, the impact of USP7 inhibition in DCs on Th1/Th2/Th17 and Treg and diabetes onset was assessed using an in vivo DC-based transfer model." (PMID 40247205, 2025). "Moreover, blockage of USP7 in tolerogenic Stat5b-CA.DCs abrogated their capacity to protect NOD mice from developing diabetes." (PMID 40247205, 2025). "USP7 expression and function are mostly investigated in various cancers and in Tregs in physiological and pathological conditions, including one study showing a low level of USP7 expression in Tregs of diabetes-prone NOD mice as compared to Tregs from diabetes-resistant mice." (PMID 40247205, 2025). "Results showed that similar to diabetes incidence in NOD mice in our mouse colony, 80–90% of NOD mice transfused with the vehicle- or USP7 inhibitor-treated NOD DCs become diabetic." (PMID 40247205, 2025). "We also found that following the USP7 blockade, DCs of NOD.Stat5b-CA mice lost their ability to protect NOD mice from diabetes, indicating the important immunoregulatory role of USP7 in the process of autoimmune tolerance mediated by tolerogenic Stat5b-CA.DCs." (PMID 40247205, 2025). "Moreover, USP7 inhibition increased Stat5b-CA.DC capacity to promote Th17 cells, restrained Th2 and Treg cells in vivo and, therefore, lost their capacity to protect NOD mice from diabetes." (PMID 40247205, 2025). "Of importance, when treated with USP7 inhibitor, DCs of NOD.Stat5b-CA mice failed to protect NOD recipient mice from developing diabetes." (PMID 40247205, 2025).
Ewing sarcoma (4 papers, 2020 to 2021). A small round cell tumor that lacks morphologic, immunohistochemical, and electron microscopic evidence of neuroectodermal differentiation. "Accordingly, synovial sarcoma cells (as represented by two cell lines and one organoid model) displayed markedly higher sensitivity to incremental doses of the USP7 inhibitor FT827 than Ewing sarcoma cells." (PMID 33361335, 2021). "Inhibitors of USP7 and USP19 have been developed, and their effects on Ewing sarcoma remain to be determined." (PMID 34060252, 2021). "Two deubiquitinases, USP7 and USP19 had been reported as vulnerabilities in Ewing sarcoma." (PMID 34060252, 2021). "Consistent with its selective detrimental effect observed in DepMap, USP7 depletion produced a significant decrease in proliferation of the SyS HSSYII and SYO1 cell lines, but not of the Ewing sarcoma A673 and RDES lines, despite comparable baseline protein expression levels." (PMID 33361335, 2021).
lymph node metastasis (4 papers, 2015 to 2025). "Clinically, large tumor size, advanced tumor stage, and lymph node metastasis were associated with elevated USP7 expression." (PMID 25519684, 2015). "Subsequently, USP7 expression was correlated to histological differentiation (P<0.01) and lymph node metastasis (P<0.05)." (PMID 34812471, 2021). "Importantly, high USP7 expression was significantly correlated with lymph node metastasis and histological differentiation in OSCC patients." (PMID 34812471, 2021). "Furthermore, the increased USP7 expression is positively correlated with cancer stage, lymph node metastasis, and tumor size." (PMID 25519684, 2015).
medulloblastoma (4 papers, 2019 to 2025). A malignant, invasive embryonal neoplasm arising from the cerebellum. "For example, USP7 inhibitor FT671 significantly inhibited the growth of medulloblastoma, colorectal, and lung tumors in mice." (PMID 32596150, 2020). "Following ZIKV infection, we observe distinct sub-cellular staining for ZIKV NS2B from 12 hpi in the aggressive paediatric USP7 ATRT and USP13 medulloblastoma cell lines." (PMID 40240536, 2025). "In cell lines of medulloblastoma origin, MDM2 showed the largest difference in dependency score with negative regulators PPM1D, USP7 and MDM4, ranked 6, 41 and 64, respectively." (PMID 34885154, 2021).
myocardial ischemia (4 papers, 2022 to 2025). A disorder of cardiac function caused by insufficient blood flow to the muscle tissue of the heart. "Accumulating studies suggested that USP7 is closely associated with the pathogenesis of various diseases, such as neurodegenerative diseases, myocardial ischemia and cancer." (PMID 35538032, 2022). "Taken together, these findings demonstrate the potential therapeutic effect of USP7 on myocardial ischemia/reperfusion injury." (PMID 35710902, 2022). "As a result, USP7 expression was increased in female mice, which suggests that USP7 is a regulator of myocardial ischemia." (PMID 35710902, 2022). "With reference to previous studies, we preliminarily identified USP7 as a regulatory factor in myocardial ischemia." (PMID 35710902, 2022). "The results showed significant myocardial infarction in mice during myocardial ischemia/reperfusion, and the final myocardial infarct size was reduced after inhibition of USP7." (PMID 35710902, 2022). "However, so far, only a few studies reported on the involvement of USP7 in myocardial ischemia/reperfusion injury and its molecular mechanism." (PMID 35710902, 2022). "Our data suggested that USP7 is a negative regulator of myocardial ischemia/reperfusion injury." (PMID 35710902, 2022). "To further investigate whether USP7 is involved in myocardial ischemia/reperfusion injury, we established a mouse I/R model and detected USP7 expression using RT-QPCR, immunohistochemical staining, and Western blot." (PMID 35710902, 2022). "Our data indicated that USP7 expression is increased during myocardial ischemia/reperfusion injury in mice, while its inhibiting suppressed the generation of oxygen free radicals and myocardial cell apoptosis, reduced myocardial tissue damage, and improved heart function." (PMID 35710902, 2022). "We employed a mouse I/R model and used sh-RNA and USP7 inhibitor P5091 to inhibit USP7 and a Western blot to measure the expression of pro-apoptotic protein BAX and examined whether USP7 can regulate myocardial ischemia/reperfusion damage by altering apoptosis." (PMID 35710902, 2022). "Therefore, targeting the USP7-mediated Keap1 degradation pathway may be a new approach to prevent myocardial ischemia/reperfusion injury." (PMID 35710902, 2022). "As a result, USP7 may become a novel therapeutic target for myocardial ischemia/reperfusion injury." (PMID 35710902, 2022). "Recently, two studies found that the expression of USP7 was significantly increased under hypoxia in cardiomyocytes, while its inhibition or knockdown of USP7 can protect the heart from hypoxia-induced cardiomyocyte injury or myocardial ischemia/reperfusion injury." (PMID 36386139, 2022). "In this study, abnormal elevation of Keap1 protein during myocardial ischemia/reperfusion was related to UPS disorder, which was confirmed by the return of Keap1 protein to normal level after treatment with USP7 inhibitor P5091." (PMID 35710902, 2022).
Obesity (4 papers, 2018 to 2023). Accumulation of substantial excess body fat. "Although its pathogenicity is not certain, since similar duplications have not been reported in the literature, there is one reported patient with larger duplication at the USP7 locus presenting with severe early-onset obesity and hyperphagia." (PMID 29441128, 2018). "Several studies have utilized chemical blockers to assess the roles of USP in metabolic disorders; e.g., GSK2643953A for USP20 in obesity, ML323 and SJB-043 for USP1 in β-cell damage, ML364 for USP2 in hypothalamic function, and HBX41108 for USP7 in diabetic foot ulcers." (PMID 36834633, 2023).
triple-negative breast carcinoma (4 papers, 2024 to 2025). An invasive breast carcinoma which is negative for expression of estrogen receptor (ER), progesterone receptor (PR), and human epidermal growth factor receptor 2 (HER2). "Moreover, the inhibition of USP7 has shown potential in triple-negative breast cancer by destabilizing FOXM1, thus suppressing tumor growth and underscoring its significance as a therapeutic target in cancer treatment." (PMID 40389405, 2025).
acute promyelocytic leukemia (3 papers, 2014 to 2023). An aggressive form of acute myeloid leukemia (AML), characterized by arrest of leukocyte differentiation at the promyelocyte stage, due to a specific chromosomal translocation t(15;17) in myeloid cells. "USP7/HAUSP can remove the monoubiquitination of PTEN and induce its nuclear export in acute promyelocytic leukemia." (PMID 33155366, 2021). "This is seen exquisitely in acute promyelocytic leukemia (APL) where PTEN is localized to the cytoplasm and the nucleus is devoid of PTEN due to USP7." (PMID 36830628, 2023).
adenovirus infection (3 papers, 2013 to 2024). "USP7-FLAG was delivered to the cells by adenovirus infection at titres resulting in expression levels close to endogenous USP7." (PMID 30367141, 2018). "In general, USP7 increasingly accumulated into dense, ring-like structures over time during adenovirus infection." (PMID 23555268, 2013). "At 48 h p.i. the virus yield was still reduced by 40.4% (APU6) or 26% (HU5), implying that USP7 is biologically significant for efficient adenovirus infection, even at the late stage of infection." (PMID 23555268, 2013). "Furthermore, EZH2 adenovirus infection further increased EZH2 expression in the aortic tissues of USP7-depleted AS mice." (PMID 39310812, 2024). "Therefore blocking the activity of USP7 could potentially be used to treat adenovirus infections." (PMID 23555268, 2013).
autism (3 papers, 2022 to 2025). Persistent deficits in social interaction and communication and interaction as well as a markedly restricted repertoire of activity and interest as well as repetitive patterns of behavior. "It is of interest that patients with a mutation in USP7 show phenotypes (intellectual disability, autism, and hypotonia) overlapping with SYS and PWS, suggesting that these disorders share pathological mechanisms in brain." (PMID 35011709, 2022). "Most patients with a USP7 mutation showed DD/ID of variable range, autism, and hypotonia, whereas dysmorphic features were not conclusive." (PMID 35011709, 2022).
breast tumors (3 papers, 2015 to 2024). "In conclusion, USP7 overexpression in breast tumors is associated with genomic instability and poor survival." (PMID 38672118, 2024). "With the expression of USP7, we found a clear association between a high expression of USP7 and an increased CIN70 score in breast tumors, which is known to be associated with poor prognosis." (PMID 38672118, 2024). "A high expression of USP7 showed a significantly decreased overall survival in comparison to patients with breast tumors with low USP7 expression." (PMID 38672118, 2024). "In this study, we investigated the impacts of an altered USP7 expression in breast tumors on CIN70, OS and OS after radiotherapy." (PMID 38672118, 2024). "For this, the upper and lower quartiles of breast tumors with high or low USP7 expression were compared." (PMID 38672118, 2024). "The CIN70 score was significantly increased in breast tumors with high USP7 mRNA expression in comparison to those with low USP7 expression with 540.7 ± 1.3 and 534.4 ± 1.6, with p < 0.01." (PMID 38672118, 2024). "We also found that mutations in USP9X and USP7 have an ominous prognostic impact in luminal, HER2-enriched, and basal-like breast tumors." (PMID 33671201, 2021). "The ubiquitin specific peptidase USP7, which is a deubiquitinating enzyme, is amplified/overexpressed in ~40 % of breast tumours in TCGA." (PMID 26427375, 2015). "The results show that deregulation of USP7 activity disrupts DNA repair in the S phase by increasing DNA replication stress and presents USP7 as a promising target to overcome the radioresistance of breast tumors." (PMID 38672118, 2024). "USP7 was shown to stabilize the estrogen α receptor and thus has an important function for the biology of these tumors, which is reflected by the in silico analysis, showing an increased copy-number of the USP7 gene in breast tumors of the luminal A and B subtypes." (PMID 38672118, 2024).